TGFB1 (transforming growth factor beta 1)
Diseases named in the same sentence as TGFB1 in open-access papers (continued):
Sharing a sentence is not in itself a finding about the gene and the disease.
Peritoneal Fibrosis (163 papers, 2005 to 2025). Disorder characterized by a wide range of structural changes in PERITONEUM, resulting from fibrogenic or inflammatory processes. "This study aimed to investigate the regulatory effect of Saikosaponin d (SSD), a monomer extracted from the plant Bupleurum, on peritoneal fibrosis and the contribution of TGFβ1/BMP7/Gremlin1 pathway cross-talk in this process." (PMID 34721005, 2021). "Together, these findings suggest that SSD can effectively inhibit peritoneal fibrosis, likely in a TGFβ1/BMP7/Gremlin1/Smad pathway dependent manner." (PMID 34721005, 2021). "The transforming growth factor-beta 1 (TGF-β)-induced epithelial to mesenchymal transition (EMT) plays a key role in the development of PD-induced peritoneal fibrosis (PF)." (PMID 34356903, 2021). "Our study suggests a role for the TGFβ1/BMP7/Gremlin1/Smad pathway in peritoneal fibrosis with potential therapeutic implications." (PMID 34721005, 2021). "The role of transforming growth factor beta 1 (TGF-β1) in the development of peritoneal fibrosis in PD-patients is well established." (PMID 27755542, 2016). "Overall, our results suggest that the TGFβ1/BMP7/Gremlin1/Smad pathway may be a potential therapeutic target for peritoneal fibrosis." (PMID 34721005, 2021). "In particular, our study has also demonstrated that the monomer SSD may be able to reverse peritoneal fibrosis by regulating TGFβ1/BMP7/Gremlin1/Smad pathway." (PMID 34721005, 2021). "We then wondered whether the TGFβ1/BMP7/Gremlin1 pathway was involved in the progress of peritoneal fibrosis." (PMID 34721005, 2021). "We have found that miR-200a is down-regulated in a rat model of PD-related peritoneal fibrosis (PF) and could inhibit transforming growth factor beta 1 (TGF-β1)-induced epithelial-mesenchymal transition (EMT) in peritoneal mesothelial cells by target ZEB1/2." (PMID 30888602, 2019). "Although blocking of TGFβ1 seems a rational and effective approach to ameliorate peritoneal fibrosis, this may be unwarranted in view of the important favourable role that TGFβ1 plays in cell immunity, proliferation and differentiation." (PMID 25384022, 2014). "Finally, our results also suggest that the monomer SSD may be able to reverse peritoneal fibrosis via regulation of the TGFβ1/BMP7/Gremlin1/Smad pathway." (PMID 34721005, 2021). "Thus, TGFβ1 promotes peritoneal fibrosis and dysfunction, PDGF-B promotes angiogenesis, IL-6 and its soluble receptor (sIL-6R) control the pattern of leukocyte recruitment during peritoneal inflammation and the IFNγ/TNFα combination promotes mesothelial cell apoptosis." (PMID 24599047, 2014). "Taken together, between the two PDFs, there are outspoken differences in levels of TGFβ1, TNFα, INFγ, and MIP-1β suggesting that macrophages played a crucial role over other cell types in modulating the response of BLS on peritoneal fibrosis and angiogenesis." (PMID 29728994, 2018). "The overexpression of TGFβ1 using an active adenovirus vector increased the expression of α-SMA and type 1 COL in a peritoneal fibrosis animal model." (PMID 24691097, 2014). "In the current study, we investigated the peritoneal gene expression of CCN2, TGFβ1, and VEGF in different stages of peritoneal fibrosis." (PMID 25384022, 2014). "In TGF-β1-stimulated HPFBs, pro-fibrotic genes (COL1A1, COL1A2, ACTA2, CTGF, FN1, and TGFB1) exhibited higher expression than in controls, which are crucial targets of sildenafil and SB204741 against peritoneal fibrosis." (PMID 38322704, 2023). "We hypothesized that CCN2, TGFβ1, and VEGF are already upregulated in early stages of peritoneal fibrosis and further overexpressed in EPS." (PMID 25384022, 2014). "However, biopsy studies in humans investigating the role of TGFβ1, VEGF, and CCN2 in peritoneal fibrosis and EPS in humans are scarce." (PMID 25384022, 2014). "Therefore, we studied peritoneal expression of CCN2, as well as TGFβ1 and VEGF, in different stages of peritoneal fibrosis." (PMID 25384022, 2014).
Peritoneal Fibrosis (continued). "In agreement, our recent data also revealed that Tanshinone IIA could attenuate peritoneal fibrosis by suppressing TGFβ1 expression." (PMID 26885500, 2015).
endometriosis (161 papers, 2005 to 2026). The growth of functional endometrial tissue in anatomic sites outside the uterine body. "Transforming growth factor-beta 1 (TGFB1) is an anti-inflammatory cytokine that has been shown to play a role in endometriosis pathogenesis and suppresses or promote endometrial cancer depending on CD73 expression." (PMID 38999962, 2024). "Secondly, the correlation between plasma and tissular levels of MMPs and TGFβ1 should be approached to offer a better perspective on the effects of RiDE in endometriosis etiopathogenesis and its adjuvant role in endometriotic lesions management." (PMID 38398530, 2024). "Levels of TGF-β1 were found to increase in the peritoneal cavity of women with endometriosis, and Tgfb1 deletion reduced the growth of endometriosis lesions in mice." (PMID 39141428, 2024). "Transcriptomic work on endometriomas showed that the inflammatory cytokine transforming growth factor beta 1 (TGFβ1), regulates other inflammatory mediators relevant to endometriosis, including tumor necrosis factor alpha (TNFα) and interleukin-6 (IL6)." (PMID 30087267, 2018). "In animal mode, TGFβ1-null mice developed fewer and smaller peritoneal endometriosis-like lesions compared with their wild-type counterparts." (PMID 28415639, 2017). "Our data supports role for ID1 in the pathophysiology of endometriosis, as an effector of TGFβ1 dependent upregulation of VEGF-A, and highlights a novel potential therapeutic target." (PMID 26577912, 2015). "We have also shown that the peritoneum from women with endometriosis expressed higher levels of TGFB1 mRNA transcripts in peritoneum adjacent to endometriosis lesions, when compared to peritoneum distal to endometriosis lesions." (PMID 25207642, 2014). "In women with endometriosis, peritoneum from sites adjacent to endometriosis lesions expressed higher levels of TGFB1 mRNA when compared to distal sites (P<0.05)." (PMID 25207642, 2014). "Furthermore, they suggested that this relationship was mediated by transforming growth factor-beta 1 (TGF-β1), which was increased in endometriosis and was related to an increased migratory, invasive and colonizing potential of endometriotic cells." (PMID 38339132, 2024). "Moreover, there is evidence that miR-21 inhibits the translation of TGFβ-1 mRNA in various diseases, including endometriosis, and the post-transcriptional regulation of miR-21 via SMAD3 plays a key role in its upregulation and the development of fibrosis." (PMID 36768775, 2023). "Thus, this study aims to determine the levels of transforming growth factor-beta 1 (TGF-β1) in menstrual blood as an angiogenic factor to the degree of endometriosis." (PMID 38116460, 2023). "This increase in TGFB1 expression may be a result of the increased inflammatory environment induced by the presence of an endometriosis lesion." (PMID 25207642, 2014). "Interestingly, TGF-β1 was identified as central component of one of four molecular endometrial/peritoneal networks identified in a model of endometriosis and TGFB1 transcripts from both the host (mouse) and endometrial (human) compartments appeared to contribute to lesion development." (PMID 25207642, 2014). "Transforming growth factor-beta 1 (TGF-β1) can promote both angiogenesis and cell growth and thus promote inflammatory reactions that ultimately lead to chronic pain in patients with endometriosis." (PMID 40004233, 2025). "In a mouse model of endometriosis, intraperitoneal administration of baicalein inhibited ectopic lesions’ growth, reduced MT1-MMP, proprotein convertase of MMPs (FURIN) and TGFB1 expression." (PMID 33919512, 2021). "Clinically, it has been observed that the expression of transforming growth factor beta 1 (TGF-β1) in the peritoneal fluid and nerve fibers surrounding lesions in patients with endometriosis is significantly higher than in control groups without endometriosis." (PMID 40004233, 2025).
endometriosis (continued). "Therefore, decreasing of TGFβ1 by the depletion of CD206+ MΦ may contribute to the recovery of NK activity and result in the reduction of endometriosis lesions." (PMID 33441630, 2021).
Stroke (160 papers, 2008 to 2025). Sudden impairment of blood flow to a part of the brain due to occlusion or rupture of an artery to the brain. "In accordance with previous publications, this study corroborates the potential of TGFβ1 and associated signaling cascades as a target for future therapeutic interventions to enhance structural plasticity and functional recovery for stroke patients." (PMID 32887692, 2020). "This proposed mechanism of TGFβ1 signaling could underly the observed increase in structural plasticity after stroke in vivo as suggested by the temporal and spatial expression of TGFβ1." (PMID 32887692, 2020). "Myeloid cells infiltrate the brain and release TGFβ1, inducing the formation of E-pericytes after stroke." (PMID 40667795, 2025). "Key EMT-related genes that were downregulated in MMP-3 KO males included Fbn1, Fbln1, Tgfb1, Tgfbr3, Snai2, and Fgf2, while female MMP-3 KO stroke brains showed downregulation of Fbln5, Fbln1, Fbln2, and Tgfb1." (PMID 39000490, 2024). "Key EMT-related genes that were downregulated upon MMP-3 KO in male stroke brains included Fbn1, Fbln1, Tgfb1, Tgfbr3, Snai2, and Fgf2." (PMID 39000490, 2024). "Key EMT-related genes that were downregulated in female MMP-3 KO stroke brains included Fbln5, Fbln1, Fbln2, and Tgfb1." (PMID 39000490, 2024). "Astrocytes have been shown to release anti-inflammatory and neuroprotective cytokines, such as TGFβ1, during the subacute phase of stroke." (PMID 38339065, 2024). "Astrocytes can release TGFβ1 with an immunoregulatory role after stroke and a neuroprotective function." (PMID 36982724, 2023). "For example, BMSCs exhibit their immunomodulatory properties in the experimental moles of heart disease and stroke by secreting transforming growth factor beta 1 (TGF-β1)." (PMID 35841007, 2022). "On the other hand, using a rat stroke model, it was suggested that TGFβ1 released by macrophages in the infarct area mediates microglia activation in the peri-infarct area and potential secondary damage to peri-infarct neurons." (PMID 34572573, 2021). "A recently published transcriptomic screen showed an upregulation of TGFβ1 in the stroke-denervated cervical hemicord of adult mice at 28 d after a large cortical stroke." (PMID 32887692, 2020). "In situ hybridization for TGFβ1 in the stroke-denervated spinal cord showed an increase of TGFβ1 mRNA at 4 dpi in both analyzed regions, the CST domain of the dorsal funiculus as well as the iGM." (PMID 32887692, 2020). "It provides a novel mechanism involving TGFB1 in compensatory axonal sprouting and growth after stroke." (PMID 32887692, 2020). "We found TGFβ1 upregulated in the stroke-denervated mouse spinal cord after ischemic injury to the motor cortex as early as 4 d postinjury (dpi) and persisting up to 28 dpi." (PMID 32887692, 2020). "This interpretation is in line with a previous finding of increased TGFβ1 expression in microglia/macrophages in the stroke penumbra early after middle cerebral artery occlusion." (PMID 32887692, 2020). "Previous studies using Activin A as an agonist at ALK4 receptors and TGFβ1 as an agonist at ALK5 receptors have shown neuroprotective properties in in vivo models of stroke." (PMID 33013673, 2020). "Endogenous TGFβ1 levels were shown to be increased in early phases after stroke, within the critical period of plasticity." (PMID 32887692, 2020). "Given the potential role of TGFβ1 in structural plasticity and functional recovery after stroke highlighted in several published studies, we investigated its downstream signaling in an in vitro model of neurite outgrowth." (PMID 32887692, 2020). "In line with a progressive elevation of the anti-inflammatory/neuroprotective response of microglia and infiltrating macrophages in the post stroke period, at 7 days Mrc1, Tgfb1 and Trem2 transcripts also significantly increased." (PMID 33246465, 2020).
Stroke (continued). "TGFβ1 is up-regulated after CNS damage or in disease states that involve microglial activation, including stroke and neurodegenerative diseases." (PMID 29780305, 2018). "Tgfb1 and Tgfbr2 mRNAs showed extremely high levels (10- to 57-fold over controls) at day 14 in post-stroke rats." (PMID 24672479, 2014). "Thus, the TGFβ1-TGFβR2 pathway is a potential therapeutic agent for promoting brain self-repair after stroke." (PMID 40667795, 2025). "Infiltrating myeloid cells produce dominant TGFβ1 in mouse brain after stroke." (PMID 40667795, 2025). "The predominant sources for brain transforming growth factor are the rMGCs and rPVMΦs following brain injury (stroke) and these cells, including the rACs, have all been shown to be capable of a marked upregulation of transforming growth factor beta-1 signaling following brain injury (stroke)." (PMID 37512148, 2023). "TGFβ1 signaling increases with age; astrocytes and activated microglia and macrophages are the main cell types that undergo increased TGFβ1 signaling in response to the post-stroke increase in TGFβ1." (PMID 35454099, 2022). "In the stroke model, astrocytes significantly increased the capillary tube-like formation of BMECs via Ang1/Tie2 and Flk1 expression, and astrocyte-derived TGFβ1 reduced tPA and TM transcription in the co-cultured BMECs, which promoted the angiogenesis and vascular stabilization after stroke." (PMID 33430164, 2021). "It has been proposed that transforming growth factor-beta 1 (TGF-β1) released by astrocytes could help preserve brain function during the subacute period after stroke limiting neuronal cell death." (PMID 33126773, 2020). "TGFβ-1 signaling has shown to be neuroprotective and increases after injury or stroke." (PMID 33115519, 2020). "Such a mechanism could be the basis on which TGFβ1 mediates compensatory sprouting of re-innervating CSN axons in the stroke-denervated spinal cord." (PMID 32887692, 2020). "Following stroke, TGFβ1 has been reported to exert neuroprotective effects." (PMID 32887692, 2020). "At this late time point after stroke, TGFβ1 expression was found to be upregulated in the cortex as well as in the stroke-denervated hemicord." (PMID 32887692, 2020). "A previous study reported an upregulation of TGFβ1 mRNA in the stroke-denervated spinal cord at 28 dpi, suggesting that TGFβ1 might serve as a local tissue-derived pro-regenerative cue for re-innervating axons after cortical stroke." (PMID 32887692, 2020). "It is well known that microglial cells are able of producing anti-inflammatory cytokines such as IL-10 and transforming growth factor-β1 (TGFβ1), which have neuroprotective effects as it was observed in experimental animal models of traumatic injury and stroke." (PMID 30518432, 2018). "Augmentation of TGFβ1 responses may therefore be beneficial in preventing inflammation in neurological disorders including stroke and neurodegenerative diseases." (PMID 26867675, 2016). "Myeloid cells could infiltrate the brain and release dominantly TGFβ1 after stroke." (PMID 40667795, 2025). "Importantly, TGFβ1 contributed to angiogenic pathogenesis in human stroke patients." (PMID 40667795, 2025). "In addition to being important in driving gliosis, transforming growth factor beta-1 also results in microvascular basement membrane remodeling with thickening due to increased AC fibronectin production following stroke, and this remodeling phase, in aged individuals." (PMID 37512148, 2023). "To address whether TGFβ1 could serve as a trigger and modulator of structural plasticity in the stroke-denervated hemicord, we evaluated the expression pattern of TGFβ1 within the dorsal funiculus and gray matter at selected, early time points after stroke (2, 4, 7, and 28 dpi)." (PMID 32887692, 2020).
Stroke (continued). "In our study TGFB1 rs1800469, LTC4S rs730012 and LTA rs909253 were associated with ischemic stroke in the non-hypertensive group, which is in line with previous reports, although these findings drew from different ethnic populations and different stroke subtypes." (PMID 22769019, 2012). "In young female mice subjected to dMCAO, the TGFβ1 protein predominantly co-localized with CD68, activated microglia and macrophages, at 3 days post-stroke." (PMID 40667795, 2025). "The TGFβ1-TGFβR2 pathway induces the transdifferentiation of ECs into pericytes, contributing to BBB restoration and neuron protection after stroke." (PMID 40667795, 2025). "Both astrocytes-derived TGFβ1 and the hedgehog agonist SAG were previously reported to maintain the vascular and BBB stabilization under stroke or HIV infection." (PMID 34281571, 2021). "Expression values for over 22,000 rat genes were scored and received a vote for each experiment in which the gene was dysregulated at 24 hours following insult (stroke, undercut, DOC, albumin, or TGFβ1)." (PMID 28794441, 2017). "We observed an upregulation of TGFβ1 mRNA at 4 dpi in the stroke-affected CST and the iGM (laminae 5–7) in the cervical spinal cord after a large stroke to the motor cortex, a time point when compensatory axonal sprouting of the CST may be triggered." (PMID 32887692, 2020).
triple-negative breast carcinoma (149 papers, 2012 to 2026). An invasive breast carcinoma which is negative for expression of estrogen receptor (ER), progesterone receptor (PR), and human epidermal growth factor receptor 2 (HER2). "LINC01824 is a lncRNA that is strongly correlated with transforming growth factor beta 1 (TGF-β1) expression in triple-negative breast cancer tissue." (PMID 38406143, 2024). "In triple negative breast cancer (TNBC), hepatic leukemia factor (HLF) was regulated by TGFB1 secreted by tumor-associated macrophages." (PMID 37091802, 2023). "To study a possible functional link between autocrine TGFβ and RAC1B, we selected two RAC1B-expressing cell lines, Panc1 (PDAC) and MDA-MB-231 (triple-negative breast cancer), known for their high production and secretion of endogenous TGFβ1." (PMID 33266416, 2020). "Its expression in triple-negative breast cancer cells is enhanced by the transcription factor RUNX2, and both, BSP and RUNX2 are under control of IGF-1 and TGFβ1." (PMID 30805306, 2019).